PPARD (peroxisome proliferator activated receptor delta)
Description:
Ligand-activated transcription factor key mediator of energy metabolism in adipose tissues. Receptor that binds peroxisome proliferators such as hypolipidemic drugs and fatty acids. Has a preference for poly-unsaturated fatty acids, such as gamma-linoleic acid and eicosapentanoic acid. Once activated by a ligand, the receptor binds to promoter elements of target genes. Regulates the peroxisomal beta-oxidation pathway of fatty acids. Functions as transcription activator for the acyl-CoA oxidase gene. Decreases expression of NPC1L1 once activated by a ligand.
Synonyms: NUC1; NR1C2; PPARB; NUCII; FAAR; NUCI
Tractability: Small molecule: an approved drug acts on it; a structure with a bound ligand is known; a high-quality ligand is known; it has a high-quality binding pocket; it belongs to a druggable protein family. PROTAC: UniProt records ubiquitination sites on it; its protein half-life has been measured; a small molecule that binds it is known.
Target class: Nuclear hormone receptor subfamily 1 group C member 2; Nuclear receptor; Nuclear hormone receptor subfamily 1; Nuclear hormone receptor subfamily 1 group C; Transcription factor
Chemical probes: CAY10592, CHEMBL1644614, CHEMBL495990, Cardarine (high quality), GW0742 (high quality), PD084720
Safety:
Unwanted effects reported when the protein is acted on. In parentheses: how it was acted on, where the effect was seen, and who reports it.
drug toxicity (source: ClinPGx)
Increased, Liver Steatosis (source: AOP-Wiki)
Gene: Protein-coding gene on chromosome 6 (35,342,530 to 35,428,193, forward strand). Ensembl gene ENSG00000112033.
Subcellular location: Nucleus
Pathways (Reactome):
Gene expression (Transcription): Nuclear Receptor transcription pathway
Metabolism: Carnitine shuttle
Signal Transduction: Signaling by Retinoic Acid
Gene Ontology:
Molecular function: DNA-binding transcription factor activity; linoleic acid binding; lipid binding; nuclear receptor activity; protein binding; sequence-specific double-stranded DNA binding; transcription coactivator binding; DNA binding; DNA-binding transcription factor activity, RNA polymerase II-specific; DNA-binding transcription repressor activity, RNA polymerase II-specific; nuclear steroid receptor activity; RNA polymerase II cis-regulatory region sequence-specific DNA binding; fatty acid binding; NF-kappaB binding; sequence-specific DNA binding; zinc ion binding
Biological process: apoptotic process; apoptotic signaling pathway; cellular response to nutrient levels; energy homeostasis; positive regulation of DNA-templated transcription; regulation of transcription by RNA polymerase II; axon ensheathment; cell differentiation; cell population proliferation; cholesterol metabolic process; D-glucose transmembrane transport; decidualization; embryo implantation; fatty acid beta-oxidation; fatty acid catabolic process; fatty acid metabolic process; fatty acid transport; generation of precursor metabolites and energy; glucose metabolic process; hormone-mediated signaling pathway; intracellular receptor signaling pathway; lipid metabolic process; negative regulation of cholesterol storage; negative regulation of DNA-templated transcription; negative regulation of inflammatory response; and 29 more
Cellular component: nucleus; chromatin; nucleoplasm; RNA polymerase II transcription regulator complex
Genetic constraint (gnomAD): Loss-of-function variants: 6 observed, 38.1 expected, observed/expected ratio (o/e) 0.16, 90% interval 0.085 to 0.31. The upper end of that interval is the gene's LOEUF score, 0.31, which puts it in group 1 of 6, group 1 being the genes least tolerant of losing a copy. Missense variants: 394 observed, 595.97 expected, observed/expected ratio (o/e) 0.66, 90% interval 0.61 to 0.72. Synonymous variants: 206 observed, 231.47 expected, observed/expected ratio (o/e) 0.89, 90% interval 0.79 to 1.
Homologues: Orthologues: chimpanzee PPARD (99% identical), macaque PPARD (99% identical), pig PPARD (95% identical), guinea pig PPARD (93% identical), mouse Ppard (92% identical), rat Ppard (91% identical), dog PPARD (90% identical), rabbit PPARD (89% identical), zebrafish ppardb (72% identical), zebrafish pparda (71% identical), tropical clawed frog ppard (61% identical), Caenorhabditis elegans sex-1 (25% identical), and 184 more. Paralogues in human: PPARA (64% identical), PPARG (56% identical), NR1D2 (30% identical), NR1D1 (28% identical), RARG (26% identical), RARA (26% identical), RARB (26% identical), RORC (25% identical), RORA (24% identical), THRB (24% identical), NR1H2 (24% identical), NR1H3 (24% identical), and 6 more.
Diseases named in the same sentence as PPARD in open-access papers:
PPARD is named in the same sentence as 285 diseases in open-access papers, as found by Europe PMC text mining. Sharing a sentence is not in itself a finding about the gene and the disease. The quoted sentences say what the papers report.
Obesity (170 papers, 2004 to 2026). Accumulation of substantial excess body fat. "Activated AMPK increases PPARδ phosphorylation and hence suppresses ER stress in high-fat-associated obesity and hypertension." (PMID 35340217, 2022). "The present study indicated that rs2016520 on the PPARD gene was associated with obesity and overweight in the Han Chinese population, and the results were similar to previous studies." (PMID 36297109, 2022). "Regarding the association between PPARD gene differentiation and obesity, numerous polymorphic SNPs have been studied, but the results presented in the literature on this topic are inconclusive." (PMID 36558537, 2022). "Genetically predisposed obese Leprdb/dbmice treated with GW501516 demonstrated a decrease in lipid accumulation, while PPARδ-deficient mice were prone to obesity on a high-fat diet." (PMID 36078043, 2022). "The current study also displayed higher BMI and WHR values in T2DM patients with PPARD rs2016520 TC and CC genotypes, which indicated a potential contribution of the genetic variant to the prevalence of overweight and obesity in T2DM patients." (PMID 36051387, 2022). "Ginger has been shown to regulate the PPARδ (peroxisome proliferator-activated receptor δ) signaling pathway in adipocytes and reduce the risk of obesity in C57BL/6J mice." (PMID 32471063, 2020). "PPARδ was shown to act as a regulator of fat burning and was identified as a potential target in the treatment of obesity and its associated disorders." (PMID 29518145, 2018). "PPARδ deficient mice are prone to obesity and insulin resistance when challenged with a high-fat diet (HFD)." (PMID 28404991, 2017). "Selective overexpression of a constitutively active form of PPARδ in mouse adipose tissue induces significant weight loss and protects against high-fat diet-induced obesity and dyslipidemia." (PMID 25360162, 2014). "By contrast, skeletal muscle-specific knockout of Pparδ seems to cause a decrease in oxidative capacity and makes mice prone to obesity and metabolic disorders." (PMID 22040534, 2011). "Impaired glucose and fatty acid metabolism due to decreased PPARδ expression also increases the risk of obesity and type 2 diabetes." (PMID 20885954, 2010). "With this purpose, we have selected highly informative polymorphisms in CAPN5, PPARG and PPARD genes and analysed it in 1953 individuals in relation to the absence or presence of obesity." (PMID 18657264, 2008). "The identification of genetic association of PPARD with obesity in our population contributes to the notion that this gene is a candidate gene for obesity and related phenotypes." (PMID 18657264, 2008). "Several groups have examined different PPARD gene polymorphism in obesity related traits, half of them with positive results." (PMID 18657264, 2008). "In the monogenic analysis, only the peroxisome proliferator-activated receptor delta (PPARD) gene was associated with obesity (OR = 1.43 [1.04–1.97], p = 0.027)." (PMID 18657264, 2008). "PPARδ was initially regarded as a promising prospect forstudies of obesity and associated diseases purely on the merit ofits pharmaceutically accomplished homologues." (PMID 17389768, 2007). "Particularly, PPARδ is highly expressed in the SM and has been shown to stimulate PGC1α expression in mice SM, while its ablation induced muscle fiber-type switching, reducing muscle oxidative capacity and consequently predisposing to obesity and diabetes." (PMID 40723425, 2025). "Notably, treatment with a PPARδ agonist reversed this effect, demonstrating its potential as a therapeutic target against obesity-associated type II diabetes." (PMID 39327610, 2024). "Additionally, in obesity-induced insulin resistance, exosomes derived from adipose tissue macrophages exhibited significant upregulation of miR-29a, which can bind to PPARδ and cause insulin resistance." (PMID 39327610, 2024). "In addition, our result suggested that PPARD is a target of fucoidan against PFOA-associated obesity." (PMID 36034923, 2022).
Obesity (continued). "PPARD agonists in mice can alleviate obesity caused by high-fat diet." (PMID 36192451, 2022). "This suggests that proper PPARδ protein activity may be associated with a reduced susceptibility to obesity." (PMID 36558537, 2022). "The regulation of PPARδ and PGC1α through overexpression of miR-29a may serve as a potential mechanism for obesity associated neurodegenerative diseases." (PMID 34690698, 2021). "However, activation of a PPARδ dependent signaling cascade by DBT would be interesting, as PPARδ is the major regulator for mobilization of fat and energy expenditure from fat and because of this phenotype potentially linked to obesity and its prevention." (PMID 25214874, 2014). "Based upon evidence that PPARδ is activated by dietary fatty acids, we hypothesized that PPARδ may be an important molecular determinant of susceptibility to environmentally induced obesity." (PMID 22916190, 2012). "Given the known role of PPARδ in the regulation of genes that promote lipid oxidation and its recognized anti-inflammatory effects in the CNS, we hypothesized that loss of PPARδ function, via genetic deletion, would lead to or potentiate obesity." (PMID 22916190, 2012). "Genetic association analysis of CAPN5 and PPARD gene variants with obesity." (PMID 18657264, 2008). "In addition, we have found a significant interaction between CAPN5 and PPARD genes (p = 0.038) that reduces the risk for obesity in a 55%." (PMID 18657264, 2008). "We have found that the PPARD polymorphism is associated with obesity in our population." (PMID 18657264, 2008). "Activation of PPARD in mouse models increased energy consumption, improved insulin sensitivity, and was protective against obesity and diabetes." (PMID 39899669, 2025). "PPARδ, which is expressed ubiquitously, influences energy expenditure and mitochondrial function, playing a role in obesity and metabolic syndrome." (PMID 40926269, 2025). "CA protects against endothelial dysfunction and oxidative stress in diabetes and obesity by targeting PPARδ through Nrf2/HO-1 and Akt/eNOS signaling pathways." (PMID 39856769, 2025). "In animal models, PPARδ agonists reduce lipid accumulation, whereas PPARδ-deficient mice fed an HFD show reduced energy uncoupling and increased obesity susceptibility." (PMID 41438090, 2025). "Obesity triggers a phenotypic change in gastric SMCs, driven by the activation of the PPARD/PDK4/ANGPTL4 pathway." (PMID 40652248, 2025). "This study reveals a novel mechanistic link between obesity and gastric smooth muscle dysfunction, implicating the activation of the PPARD/PDK4/ANGPTL4 pathway." (PMID 40652248, 2025). "Peroxisome proliferator-activated receptor delta (PPARδ) regulates anti-inflammatory responses and is protective in several diseases such as obesity and cancer." (PMID 39519830, 2024). "Relationships of the polymorphisms in fat mass and obesity-associated gene (FTO) and peroxisome proliferator-activated receptor delta gene (PPARD) with metabolic-related diseases remain to be clarified." (PMID 38161971, 2023). "Here, on the basis of PPARs functions, we are the first to report that BBR activates PPARδ to regulate downstream genes to inhibit adipogenesis, thereby suppressing obesity." (PMID 37511356, 2023). "Generally, the elevation of energy consumption rate is an important factor in obesity and hypertension, and PPARδ, AMPK, and PGC-1α are involved in catabolic metabolism producing ATP." (PMID 37168052, 2023). "While there are currently no PPARδ agonists in clinical use, promising studies in animals have demonstrated that activating PPARδ has beneficial effects on obesity, hypercholesterolemia, insulin resistance, and exercise endurance." (PMID 35413288, 2022). "Recent studies with herbal supplements such as bavachinin (a pan-PPAR agonist) from the glucose-lowering malaytea scurfpea herb and ginger (a PPARδ agonist) reduced obesity in obese db/db mice, and diet-induced obesity in C57BL6J mice, respectively." (PMID 36078043, 2022).
Obesity (continued). "PPARD agonists can promote cholesterol accumulation in macrophages, reduce obesity, increase fatty acid oxidation and oxidative phosphorylation in skeletal muscle, and increase insulin sensitivity." (PMID 36090166, 2022). "Potent associations have been determined between genetic variation in the PPARD gene and elevated susceptibility to T2DM, as well as obesity and insulin resistance." (PMID 36051387, 2022). "The peroxisome proliferator-activated receptor δ (PPARδ) stimulators exhibited anti-obesity effects." (PMID 35949312, 2022). "The findings represented that following the activation of the PPARδ pathway with ginger, obesity was reduced, and exercise tolerance capacity developed by elevating skeletal muscle fat catabolism." (PMID 35949312, 2022). "In vivo experiments with PPARδ agonists have examined their effects in a variety of diseases and cellular processes, including diabetes, obesity, and lipid metabolism." (PMID 36078043, 2022). "PPARδ activation stimulates fatty acid β-oxidation in adipocytes and skeletal muscle, depletes lipid accumulation and attenuates obesity." (PMID 34439415, 2021). "Current research suggests that ginger extract (containing 6-shogaol and 6-gingerol) alleviates diet-induced obesity and improves the exercise capacity of the body by increasing fat catabolism in skeletal muscle due to the activation of the PPARδ pathway." (PMID 32471063, 2020). "In contrast, in the liver, obesity led to higher expression of Pparα and Pparδ expression in older female livers compared to young females while ADRB3 stimulation led to downregulation of Pparα and Pparδ expression." (PMID 31983693, 2020). "In mice with an intestinal epithelial cell-specific deletion of PPARδ, intestinal PPARδ protected against diet-induced obesity, insulin resistance, and dyslipidemia." (PMID 31073415, 2019). "Together, these results suggest targeting of intestinal PPARδ as a potential approach for the therapeutic treatment of dyslipidemia, obesity and insulin resistance, with limited systemic toxicity." (PMID 28404991, 2017). "Peroxisome-proliferator-activated receptors (PPARs) are the nuclear hormone receptor including PPARα, PPARδ, and PPARγ, which play a critical role in regulation of obesity, cardiovascular diseases, and inflammation." (PMID 28293264, 2017). "Here we show that intestinal PPARδ contributes to the protection against diet-induced obesity and that intestinal PPARδ is required for mediating the increase in plasma levels of HDLc by PPARδ activation." (PMID 28404991, 2017). "Using mice with an intestinal epithelial cell-specific deletion of PPARδ, we show that intestinal PPARδ protects against diet-induced obesity, insulin resistance and dyslipidemia." (PMID 28404991, 2017). "Selective knock-in of PPARD in adipose tissue of Lepdb/db mice reduces lipid accumulation and prevents obesity in mice." (PMID 28814270, 2017). "Together, these results show that intestinal PPARδ protects against HFD induced obesity, insulin resistance and dyslipidemia." (PMID 28404991, 2017). "Although it has been reported that induction of peroxisome proliferator-activated receptor delta (PPARδ) drives KCs toward the M2 form, reducing obesity-induced insulin resistance in mice, the role of M2 KCs in NAFLD is still not elucidated." (PMID 27657051, 2016). "Studies have shown that ATRA represses obesity and insulin resistance in a type 2 diabetic animal model, through activation of proliferation-activated receptor δ (PPARδ)." (PMID 26237391, 2014). "In an animal model, Wang et al24 suggested that activation of PPARδ through a selective agonist reduced fatty acid storage in adipocytes and prevented development of obesity in animals fed a high-fat diet." (PMID 23545576, 2013).